EPCAM (epithelial cell adhesion molecule)
Diseases named in the same sentence as EPCAM in open-access papers (continued):
Sharing a sentence is not in itself a finding about the gene and the disease.
cancer (continued). "Possible explanations of this cell loss are a smaller size and greater flexibility of the CTC in cancer patients as compared to the cell lines and a lower expression of the EpCAM antigen on the CTC in cancer patients as compared to the cell lines." (PMID 30678037, 2019). "EpCAM, which is commonly used for the detection of CTCs in other cancers, is only expressed in approximately 35% of HCC cases." (PMID 31141571, 2019). "This has relied on surface proteins such as the Epithelial Cell Adhesion Molecule (EpCAM) to confirm/refute their origin as cancer cells." (PMID 31319587, 2019). "Totally, the sensitivities of EpCAM-based detection methods seemed to be significantly lower than EpCAM-independent detection methods due to the down-regulation of EpCAM in cancer cells during epithelial-mesenchymal EMT process." (PMID 31878900, 2019). "Recently we reported the ability of SPRi to consistently detect EpCAM expression on various viable cancer cells, analyzing them in real time and label free." (PMID 31137820, 2019). "In fact, EpCAM has been found to be expressed in most types of epithelia, engaging in cell proliferation, migration, invasion, cell cycle regulation, and cancer initiation." (PMID 31886299, 2019). "Yet there are several reports which state that suppression of mTOR decreases activity of Aldh1 as well as EpCAM, the well-known markers for cancer stem cells." (PMID 31729456, 2019). "More recently, nanostructured cell-affinity substrate coated with cancer-cell capture agents (e.g., epithelial cell adhesion molecule antibody, anti-EpCAM) has also been applied to enrich and immobilize CTCs, exhibiting improved cell-capture efficiency." (PMID 30658713, 2019). "We found the subpopulation of cells expressing the cancer-initiating cell marker EpCAM to proliferate in response to low 5-FU doses." (PMID 31013771, 2019). "Last but not least, our results do not allow for comparison of ldEVs between healthy individuals and cancer patients since the available image data sets of patients corresponded to only EpCAM enriched samples." (PMID 31434250, 2019). "The human cancer stem cell marker EpCAM and pluripotency genes Nanog homebox, Oct4 (also known as POU class 5 homeobox 1) and Sox2 do not match HOTAIR’s role as an oncogenic factor." (PMID 31097003, 2019). "The most commonly employed antibody is EpCAM, but several devices employ a cocktail of antibodies that can be specialized for the particular cancer being studied." (PMID 31174404, 2019). "A higher capture efficiency (84.93–95.21%) has been achieved for EpCAM-expressing cancer cells, while for EpCAM-negative cells (Hs578T cells), the efficiency remained relatively low." (PMID 31088479, 2019). "EpCAM and its signaling internal domain EpIC have been implicated in cancer stemness and the EMT process, suggesting that EpCAM is more than just a marker for CTCs." (PMID 31225512, 2019). "Using EpCAM to define 4 T1 cancer stemness, EpCAM(+) cells were reduced in shMCT-1 (#3–28) mammospheres (65.6%) than in the scramble control (100%), and tocilizumab further decreased the EpCAM(+) populations (28.9%) in the shMCT-1 background." (PMID 30885232, 2019). "One interesting strategy was used by Balasubramanyam and collaborators in a recently published work, where they designed aptamer-siRNA chimeras with great specificity to cancer expressing EpCAM that can deliver siRNAs against chosen oncogenes." (PMID 31888119, 2019). "There are only a few aptamers against stem cells markers such as cancer stem cells (CSCs), including cancer cell surface biomarkers: Epithelial cell adhesion molecule (EpCAM), CD133, CD117, and CD44, and those for mouse embryonic stem cells." (PMID 30866536, 2019). "EPCAM is also a gene closely related to poor differentiation 33, and its expression was found to be decreased by CA in both cancer cell lines, although its expression reduction in microarray was not substantial." (PMID 31660066, 2019).
cancer (continued). "Epithelial cell adhesion molecule (EpCAM), one of the transmembrane glycoproteins that is closely related with cancer metastasis, is highly expressed on many cancer cells." (PMID 31010258, 2019). "Our results indicate that FF-nPES performs similarly to EV ELISA, when analyzing EV surface expression of epithelial cell adhesion molecule (EpCAM), which has clinical significant as a cancer biomarker." (PMID 31921310, 2019). "The CTC recovery rate, white blood cell depletion rate, and purity of CTCs isolated using the positive and negative methods were analyzed using blood samples spiked with cancer cells with different expression levels of EpCAM." (PMID 31181790, 2019). "EpCAM accounts for >90% of cancer mortality and represents an ideal biomarker candidate for cancer cell detection and monitoring." (PMID 31010258, 2019). "An interesting work has used DOX to inactivate cancer stem cells (CSC) by conjugating this drug to engineered RNA aptamers raised against CSC surface marker epithelial cellular adhesion molecule (EpCAM)." (PMID 31888119, 2019). "In summary, by using G6 PAMAM as the assembly component, we have developed a label-free electrochemical immunosensor for cancer cell detection based on the recognition between Anti-EpCAM and EpCAM on a modified electrode surface." (PMID 31010258, 2019). "The same group extended the investigation to new approaches to tackle cancer stem cells using EpCAM aptamer." (PMID 31888119, 2019). "EpCAM is a cancer stem cell marker, which has the potential for self-renewal, pluripotency, and is resistant to chemotherapy or radiation therapy." (PMID 31361893, 2019). "In HCC, the loss of HNF4 and expression of the cancer stem cell (CSC) markers CD44, CK19, Sox9, and EpCAM are considered to be indicators for poor prognosis." (PMID 31726709, 2019). "The epithelial cell adhesion molecule (EpCAM) is a transmembrane glycoprotein that is expressed by most human carcinomas." (PMID 31426611, 2019). "In blood spiking experiments with carcinoma cells that have high levels of EpCAM, the sensitivity to detect CTCs is higher than 85%, but with cells that express low levels of EpCAM, the sensitivity is about 42%." (PMID 31404988, 2019). "EpCAM is a 40 kDa glycoprotein initially identified as a marker for carcinoma, and further studies revealed EpCAM as a prevalent protein also expressed by normal epithelia; however, at a lower level than by carcinoma cells." (PMID 30871104, 2019). "Contrary to healthy epithelia, the distribution of EpCAM varies depending on the type of carcinoma, from a basolateral to a homogenous whole cell membranous distribution." (PMID 31225512, 2019). "EpCAM therefore became the most commonly used epithelial marker for the capture of CTCs in the blood circulation of carcinoma patients." (PMID 31225512, 2019). "EpCAM is a transmembrane glycoprotein and appears to play a role in tumorigenesis and metastasis of carcinomas." (PMID 31443698, 2019). "The epithelial cell adhesion molecule (EpCAM) is a 40 kDa epithelial antigen that is expressed on the surface of most human epithelial carcinomas (e.g., lung, colon, and breast)." (PMID 31480515, 2019). "Especially high abundant levels of EpCAM expression can be observed in carcinomas derived from colon, intestine, breast, lung and prostate." (PMID 31225512, 2019). "EpCAM is expressed in normal epithelial cells but is generally upregulated in carcinoma cells compared with healthy epithelia and the recruitment of this protein to EVs has been described in cell lines and patient biological fluids." (PMID 30765839, 2019). "The EpCAM protein was discovered almost 40 years ago as a major epithelial carcinoma antigen by M. Herlyn and colleagues, as a result of its property to generate monoclonal antibodies binding specifically to human colorectal carcinoma cells." (PMID 31225512, 2019).
cancer (continued). "EpCAM is frequently expressed in a variety of normal human epithelial tissues, mostly on basolateral membrane, progenitor and stem cells, and carcinomas." (PMID 31361893, 2019). "In proof-of-concept experiments, an epithelial marker enriched in carcinoma cells, EpCAM, was identified in EVs from cell lines and directly in urine samples." (PMID 30765839, 2019). "EpCAM is expressed in various carcinomas such as those in the colon and rectum, prostate, liver, esophagus, lung, head and neck, pancreas, and breast." (PMID 30871104, 2019). "EpCAM was shown to be hyperglycosylated in carcinoma tissue as compared with autologous normal epithelia." (PMID 31225512, 2019). "The epithelial cell adhesion molecule (EpCAM), or CD326, was one of the first cancer biomarkers that were discovered in the 1970s." (PMID 29329202, 2018). "Recent studies have established that EpCAM is overexpressed on CSCs from several cancer types, including breast, colon, pancreas, and prostate tumors." (PMID 28290053, 2018). "These include a human scFv-doxorubicin loaded liposome; two scFv conjugates, a humanized anti-EpCAM scFv-immunotoxin conjugate; and an anti-fibronectin extra-domain B human scFv for cancer indications." (PMID 29520274, 2018). "In normal cells, EpCAM is localized to the basolateral membrane, but during cancer progression, the expression pattern changes to an intense uniform over-expression." (PMID 30586898, 2018). "Briefly, αEpCAM ferrofluid is incubated in blood samples of cancer patients and binds to EpCAM+ CTCs and tdEVs." (PMID 30384500, 2018). "A bispecific T cell engager (BiTE) antibody recognizing EpCAM has also been developed for cancer treatment." (PMID 30112355, 2018). "Similar to RCC, other type of cancers, including lung and ovarian still have difficulty in capturing heterogeneous CTCs and finding clinical importance of CTCs captured by EpCAM-based methods." (PMID 30315187, 2018). "During cancer cell dissemination the epithelial surface marker EpCAM can be downregulated by either DNA methylation, glycosylation or proteolytic cleavage allowing the cancer cells to switch to a more mesenchymal and invasive phenotype." (PMID 29463222, 2018). "In cancer cells, expression of epithelial cell adhesion molecule (EpCAM) was related to high miR-181 levels." (PMID 30210551, 2018). "This EpCAM specificity in targeting cancer cells in vitro is supported by other reports demonstrating similar antigen-dependent targeting using this membrane protein." (PMID 30140380, 2018). "In the present study, we found that BIO induced the expression of the cancer stem cell markers EpCAM, CD44, KRT19, and MYC above the levels seen in MeBIO controls without inducing cytotoxicity." (PMID 30177680, 2018). "It has shown good clinical use in multiple types of advanced cancers, including breast cancer, prostate cancer, and colon cancer; however, clinical studies showed low sensitivity of the EpCAM-based enrichment in the CTC detection of NSCLC patients." (PMID 29352248, 2018). "This allows scientific information acquired on AGR2 and EpCAM pathway regulation to be translated into novel therapeutics that target the AGR2:EpCAM axis for improved cancer management." (PMID 29339412, 2018). "We have shown that cancer cell aggregation led to formation of hypoxic tumoroids with robust secretion of EpCAM-exosomes and marked upregulation of reprogramming and stemness genes as increased CIC/CSC traits." (PMID 30364132, 2018). "EpCAM was first identified as a cancer-specific cell surface antigen during a functional screen in which cancer cells were injected into mice to generate antibodies." (PMID 29329202, 2018). "We have reported both EpCAM-dependent and -independent capture of cancer cells using the polymer CTC-chip." (PMID 30104638, 2018).
cancer (continued). "The mechanistic investigation using inhibitors targeting AKT and mTOR revealed that AKT/mTOR signalling activation is important for the oncogenic effect of EpCAM on cell invasion and stem-like properties of cancer cells." (PMID 29305578, 2018). "In the following we will compare our results on EpCAM function in MDCK epithelial cells with results obtained in embryos in vivo or with results obtained with different cancer cell lines." (PMID 30304739, 2018). "By downregulating Wnt/β-catenin signaling and EpCAM gene and protein expression, Pimozide reduced cancer cellular proliferation and viability and increased apoptosis induction in HCC cells." (PMID 30112355, 2018). "In cancer cells, EpCAM regulates cell-cell adhesion and proliferation, the later based on regulated intramembrane proteolysis (RIP) and nuclear translocation of the intracellular domain EpICD17,18." (PMID 29379062, 2018). "The majority of these studies have investigated the specificity of these EpCAM aptamers to several different cell lines, representing a number of different cancer types, and suggest potential future directions for developing targeted therapeutics." (PMID 30586898, 2018). "It has been demonstrated that EpCAM positive cells play a relevant role in cancer progression and have been identified as a molecular biomarker for chemoresistance." (PMID 30112355, 2018). "As was repeatedly reported, RIP of EpCAM is a process that occurs in cancer cells and results in the presence of EpEX in the serum of cancer patients." (PMID 30261040, 2018). "Particularly, it was suggested that cancer stem cells benefit from activated EpCAM for proliferation, self-renewal, and anchorage-independent growth and invasiveness." (PMID 29652830, 2018). "EpCAM has been targeted in clinical trials using monoclonal antibodies in different types of cancer, and it is believed that this molecule represents a new target for HCC gene therapy." (PMID 30112355, 2018). "In the present study, we utilized site-specific conjugation technology to develop a novel APC that targets EpCAM (EpCAM-IR700) for use as an anti-cancer therapy." (PMID 30140380, 2018). "Alternatively, EpCAM-blocking antibodies provide a means of selectively killing cancer stem cells and inhibiting EpCAM’s mitogenic signaling activity." (PMID 29541416, 2018). "The aptamers generated are highly specific to targeting the EpCAM biomarker on cancer cells, as a result, this suggests the promising applications of utilising aptamers as in vivo molecular imaging agents." (PMID 30586898, 2018). "EpCAM-AsiC subcutaneously administered at 5 mg/kg every three days for two weeks suppressed cancer growth in a EpCAM-positive TNBC xenograft model." (PMID 29301363, 2018). "EpCAM is highly expressed in most cancers with an epithelial origin and acts as an oncogenic signaling protein." (PMID 29435146, 2018). "In this study, higher expression of EpCAM was found in NPC samples compared with non-cancer nasopharyngeal mucosa by qRT-PCR." (PMID 29305578, 2018). "In conclusion, we have developed an IgG format APC targeting EpCAM utilizing site-specific conjugation technology (Actibody technology) to be used for cancer treatment in conjunction with PIT." (PMID 30140380, 2018). "Next, the dose-dependency of the EpCAM BiTE was evaluated against PC3 cancer cells at an E:T ratio of 10:1 using the CI parameter and % cytolysis." (PMID 29499048, 2018). "Epithelial cell adhesion molecule (EpCAM) is a cancer stem cell (CSC) marker that is expressed in various epithelial carcinomas, including EAC." (PMID 30116994, 2018). "We also found that the cancer stem cell markers EpCAM, CD133, and E-cadherin were either expressed at low levels or were absent in IHOSE cells, and none of the five IHOSE cell lines formed colonies in the anchorage-independent soft agar assay." (PMID 30296284, 2018).
cancer (continued). "We further tested the utility of the real-time potency assay using freshly isolated PBMCs in combination with BiTEs antibody directed against EpCAM, a known marker for various cancers of epithelial origin." (PMID 29499048, 2018). "Collectively, the EpCAM aptamers have proven their application for effective delivery of anticancer agents and reversal of chemoresistance for killing cancer stem cells." (PMID 29301363, 2018). "Second, mesenchymal-like cancer cells are likely to escape from CellSearch system detection, which is based on epithelial markers, such as EpCAM and CKs." (PMID 29925382, 2018). "They clearly showed that EpCAM has a potential to be a direct transcriptional target in the Wnt/β-catenin signaling pathway that participates in governing the self-renewal of cancer cells." (PMID 30177680, 2018). "M6-Hh tumors had a higher proportion of CD61hi cells, previously shown to be a marker of mouse mammary CSCs15, within the EpCAM+CD24hiCD29+ cancer cell population (55.3% in M6-Hh tumors vs. 36.4% in M6-Ctrl tumors)." (PMID 30042390, 2018). "In this study, we investigated the effect of OPN on HCV replication and IFN signaling in cancer stem cells (CSCs) positive for epithelial cell adhesion molecule (EpCAM) and CD44." (PMID 30177680, 2018). "Recently, several groups demonstrated that EpCAM-targeting aptamers are good tools for siRNA delivery into epithelial cancers and cancer stem cells." (PMID 29301363, 2018). "EpCAM-independent CTC isolation has been studied using the fact that epithelial-originated cancer cells are usually larger than hematological cells." (PMID 30424286, 2018). "FACS results indicated that the Parsortix system recovered an average of 5 EpCAM+ cancer cells (20-35%) from blood samples initially spiked with 20 SkBr3 cells." (PMID 29467948, 2018). "Recent studies have revealed that EpCAM is involved in cell signalling, migration, proliferation and differentiation, as well as in metastasis and cancer stem cells." (PMID 29305578, 2018). "Several approaches such as anti-EpCAM antibodies and synthetic oligonucleotide were generated to target cancer." (PMID 28290053, 2018). "The epithelial cell adhesion molecule (EpCAM)-based separation method (CellSearch) showed good clinical use in multiple types of cancer." (PMID 29352248, 2018). "Next, we treated the dissociated cell preparations with AdipoRon followed by staining with PI and FITC-labelled EpCAM antibody to evaluate cancer cell death by counting PI−EpCAM+ and PI+EpCAM+ cells." (PMID 30038429, 2018). "In the next step, we processed blood samples from 36 cancer patients and 12 healthy donors (cohort 1) using protocol A and measured the gene expression levels of EpCAM, MAL2, PPIC, and TUSC3 in the enriched cell fractions." (PMID 29416657, 2018). "RNA aptamer EpDT3, with optimized sequence and simpler structure, is easy to be chemically synthesized and has high targeting efficiency to EpCAM-positive cancer cells." (PMID 29467932, 2018). "Epithelial cell adhesion molecule (EpCAM) is a type I transmembrane glycoprotein with a molecular weight of 40 kDa that is highly expressed on human carcinomas." (PMID 30140380, 2018). "Epithelial cell adhesion molecule (EpCAM) is known to be highly expressed in a variety of epithelial carcinomas, and it is involved in cell adhesion and proliferation." (PMID 29305578, 2018). "EGFR and EpCAM were expressed in suprabasal layers of normal mucosa and were strongly expressed in primary carcinomas, with a frequent coexpression at the single-cell level." (PMID 30261040, 2018). "Since these initial discoveries, EpCAM expression has been observed in almost every major epithelial carcinoma, including Barrett’s adenocarcinoma and ESCC." (PMID 30116994, 2018). "This was further confirmed by performing dual staining with rVAR2 and an anti-EpCAM antibody on nine different carcinoma cells lines, followed by flow cytometry analysis." (PMID 30115931, 2018).